AR (androgen receptor)
Diseases named in the same sentence as AR in open-access papers (continued):
Sharing a sentence is not in itself a finding about the gene and the disease.
breast carcinoma (continued). "A subclass of TNBC known as “molecular apocrine” cancers are defined by coexpression of AR and FOXA1 as well as a luminal breast cancer signature, despite lacking ER expression." (PMID 34680352, 2021). "Routinely, in breast cancer at immunohistochemistry, the ER, HER2 and PR statuses are determined, but not the AR." (PMID 32218303, 2020). "We used as control the human breast cancer cell line MCF7, which showed high expression levels of ERα (as expected), no expression of ERβ and weak but detectable expression of AR." (PMID 32132580, 2020). "The role of AR in KIRC progression is not clear, but it has been shown that in prostate and breast cancer cells AR binds to IGF1R promoter and thus increases IGF1R expression." (PMID 31888623, 2019). "Furthermore, we revealed that SIRT1 deficiency is associated with substantial induction of acetylated markers on six breast cancer-related gene promoters: AR, BRCA1, ERS1, ERS2, EZH2, and EP300, suggesting an active role of SIRT1 in regulating the expression of these genes in BC." (PMID 30380732, 2018). "This analysis demonstrated significant heterogeneity in AR expression in both TNBC and non-TNBC breast cancers." (PMID 28840192, 2017). "According to AR status, TNBC is divided into two subtypes as follows: AR-positive TNBC or Quadruple Negative breast cancer." (PMID 28583190, 2017). "As a new subtype of breast cancer, molecular apocrine breast cancer (MABC) is estrogen receptor (ER) and progesterone receptor (PR) negative expression, but androgen receptor (AR) positive expression." (PMID 27340922, 2016). "Based on our previous data in bone metastases from breast cancer, and on the fact that bone metastases are the hallmark of progressive disease and CRPC, mainly characterized by AR alterations, we investigated whether and how ERRα is involved in bone progression of CRPC (AR-negative) models." (PMID 27776343, 2016). "Mammary carcinoma with apocrine differentiation is composed of type A and type B cells with typically GCDFP15 and androgen receptor positive, estrogen and progesterone receptors negative." (PMID 26055980, 2015). "In ERα negative breast cancer, ERBB2 overexpression significantly correlates with high AR and ERBB3 expression." (PMID 23593223, 2013). "Since meta-analysis can help to summarize studies on specific topics, the current work also involved a meta-analysis, which compared AR positive versus AR negative expression for DFS and OS in patients with breast cancer." (PMID 24324816, 2013). "Separating the samples by TNBC status decreases this p value by 10-fold, and adding AR-negative samples to the TNBC cohort, referred to as quadruple negative breast cancer (QNBC), further increases the significance of the difference." (PMID 24155918, 2013). "We cloned a full-length cDNA of human AR, and expressed this transgene in MCF-10A non-tumorigenic human breast epithelial cells and MDA-MB-231 human breast-cancer cells." (PMID 22321971, 2012). "Regarding disease stages, AR positivity was similar between early (Stages I/II) and late-stage breast cancer (Stages III/IV), with 71.4% and 69.0%, respectively, expressing AR, suggesting that AR expression does not vary significantly with cancer stage (OR: 0.9, 95% CI: 0.3–2.5)." (PMID 40734715, 2025). "Unfortunately, depending on the threshold used to define AR-positivity, ~65–88% of TNBC patients are AR-negative and are thus classified as having quadruple-negative breast cancer or QNBC, and AR-targeted treatments are unlikely to significantly benefit this patient subgroup." (PMID 39335162, 2024). "Given that in 54.7% of our breast carcinomas, NST showed strong AR positivity, AR IHC may not be optimal for verifying apocrine differentiation." (PMID 38790919, 2024). "However, this cut-off value of AR did not predict the survival of all HER2+ and HER2+HR− breast cancer patients." (PMID 37085500, 2023).
breast carcinoma (continued). "In contrast to findings in AR+ TNBC, together these results suggest that 1 h pretreatment of apalutamide, or darolutamide, like enzalutamide, does not result in radiosensitisation of AR+/ER+ breast cancer cells in vitro." (PMID 35618789, 2022). "The Western blots illustrated that the isogenic SKBRM cell lines used in the in vivo and in vivo models did not express the androgen receptor to an appreciable extent, precluding KCZ and KCZ-7 from inhibiting tGLI1-positive breast cancer through androgen receptor antagonism." (PMID 36077791, 2022). "As with AR, GR (NR3C1) expression is not routinely evaluated in breast carcinomas." (PMID 34638457, 2021). "However, DHT-induced cell proliferation in ER-positive MCF-7 breast cancer cells is inhibited by an ER-α antagonist, ICI 182,780, but not by the AR inhibitor flutamide." (PMID 32326308, 2020). "Similarly, in luminal ERα-positive breast cancer cell lines, AR exerts an anti-proliferative effect while in MDA-MB-453, a model of ERα-negative apocrine disease, activated AR can induce cancer growth." (PMID 31684907, 2019). "Preliminary findings of improved BMD in some patients on dasatinib plus letrozole, and of AR and HER family expression in the primary breast cancers of patients who did not benefit from dasatinib plus letrozole could warrant further investigation." (PMID 31667338, 2019). "There is increasing evidence that Androgen Receptor (AR) expression has prognostic usefulness in Triple negative breast cancer (TNBC), where tumors that lack AR expression are considered “Quadruple negative” Breast Cancers (“QNBC”)." (PMID 29912871, 2018). "In addition, AR inhibition did not affect HER2 and HER3 protein expression in HER2 + breast cancer cells." (PMID 29109513, 2017). "Difficulty in handling and manipulation of an in vitro study could not find out details of subcellular molecular mechanisms between AR and FOXA1 and many other ER-positive, luminal subtype breast cancer cell lines were not investigated." (PMID 29137314, 2017). "Therefore, in the current study, we emphasized analyzing the characteristics of a unique breast cancer molecular subgroup, MABC, which is characterized by ER and PR negative, but AR positive." (PMID 27340922, 2016). "When enzalutamide-treated breast cancer cells were incubated with CEA-specific CTLs, their sensitivity to CTL-mediated lysis was improved regardless of AR expression, as the sensitivity of AR- MDA MB 231 cells was increased to the same extent as AR+ ZR75-1 and BT549 cells." (PMID 27015557, 2016). "Up to 30% of human breast cancers are driven by overactive ERBB2 signaling and it is not clear whether AR expression affects any steps of tumor progression in this cohort of patients." (PMID 23593223, 2013). "Given that of all the breast cancer models investigated, the MDA-MB-453 cell line is the only one in which AR signaling can promote rather than inhibit proliferation, increased or preferential interaction with FOXA1 over GATA3 or other factors may underpin this distinct biology." (PMID 38317241, 2024). "Cooperative promotion of luminal differentiation by AR and GATA3 also mechanistically unites independent studies linking expression of one or the other factor with a more differentiated, less proliferative phenotype in breast cancer cells regardless of molecular sub-type." (PMID 38317241, 2024). "The important role of AR in regulating GPX4 expression has recently been confirmed by AR overexpression in HEK‐293 cells and AR knockdown in ferroptosis‐resistant triple‐negative LAR breast cancer cells, and this counter‐regulation correlates with ferroptosis sensitivity." (PMID 36658724, 2023). "These and similar results in the AR-positive, ER-positive, ErbB2 active cell line, BT474, suggest that suppression of androgen signalling results in increased DNA damage and/or decreased repair in breast cancer cells that express AR, independent of ER and ErbB2 activity." (PMID 27109210, 2016).
breast carcinoma (continued). "In this study, we found that estrogen receptor β (ERβ) was more highly expressed in RCC cell lines (A498, RCC-1, 786-O, ACHN, and Caki-1) than in breast cancer cell lines (MCF-7 and HBL-100); however, no androgen receptor (AR) or estrogen receptor α (ERα) could be detected by western blot." (PMID 23460808, 2013). "On the contrary, as AR for the non-steroidal AIs presents a pro-death role, the reduction in its expression induced by CBD may not be beneficial, which may explain why their combination with CBD did not improve the anti-proliferative effects of these AIs on breast cancer cells." (PMID 37173983, 2023).
prostate tumors (500 papers, 1998 to 2026). "In contrast, the rhythmic expressions of CCCGs and NRs were significantly disrupted in TGMAP prostate tumors, with a concurrent loss of androgen receptor expression." (PMID 40948103, 2026). "Different molecular subtypes are associated with distinct AR activity in treatment-naïve prostate tumors." (PMID 40867349, 2025). "Accordingly, 2–18% of prostate tumors show point mutations in the AR gene, and gene amplifications have been reported in 5–52%, preferably in castration-resistant PCa subtypes." (PMID 41009328, 2025). "Apart from regulating transcription of key cancer-associated genes in prostate tumours, t-CDKs also play critical roles in AR expression and activity." (PMID 40163908, 2025). "While adenocarcinoma is the predominant histological variant of CRPC, a quarter of resistant prostate tumors undergo cellular reprogramming and shed their dependence on the AR, thus evading therapies and proliferating." (PMID 40746825, 2025). "Deoxy-14,15-dehydroisoaustamide from fungus Penicillium dimorphosporum breaks down resistance-linked androgen receptor variants, reactivating enzalutamide's effectiveness (androgen receptor blockers) against resistant prostate tumors." (PMID 40406006, 2025). "Taken together, these data indicates that pACK1/pSHP2 signaling promotes prostate tumors growth by overcoming pY54-H3 marks, causing increased AR expression." (PMID 38965223, 2024). "PTP-1B expression can be induced through stimulation of the AR and is associated with nuclear localization of the AR and a higher Ki67 in primary prostate tumors." (PMID 38706600, 2024). "As expected, the NEPC lesion was characterized by loss of AR signaling as indicated by depletion of androgen-responsive gene expression as compared to the primary prostate tumor." (PMID 39349591, 2024). "This is evidenced by the superior performance of the enzalutamide-based PROTAC (ARCC-4) over enzalutamide in prostate tumor cells with point mutations (F876L and T877A) in the AR." (PMID 38339414, 2024). "The cistromes of the forkhead box protein A1 (FOXA1) and homeobox protein HOXB13, two essential pioneer factors associated with the AR and AR-V7, are also altered in prostate tumors." (PMID 36768610, 2023). "Classical ADT to inhibit prostate tumor growth also affects tumor-associated T cells by influencing T cell-intrinsic AR signaling, preventing T cell exhaustion and overcoming immunotherapy resistance." (PMID 37738978, 2023). "AR target genes selectively regulated between untreated and treated prostate tumors or associated with response or resistance to therapy have been reported." (PMID 36768610, 2023). "In a retrospective analysis of a large cohort of primary and advanced prostate tumors, we observed increased expression of androgen receptor splice variants in therapy refractory tumors." (PMID 36139600, 2022). "Loss of human prostate tumor basal cell signatures was identified in basal cells of stromal AR-deficient mice." (PMID 36323713, 2022). "Loss of human prostate tumor basal cell signatures reveals in basal cells of stromal AR-deficient mice." (PMID 36323713, 2022). "Among men with localized prostate cancer, expression of genes proximal to AR sites lost in the transition from normal prostate to prostate tumor was associated with clinical outcome." (PMID 35509021, 2022). "In this work, we report that C4S is upregulated in prostate tumors after the loss of AR signaling and that this event supports survival, proliferation, and metastases formation in AR-indifferent CRPC." (PMID 35963852, 2022). "This upregulation of CHST11 after AR inhibition or loss was confirmed in three independent human prostate tumor cohorts (VPC, IST, and UW cohorts) of 435 patients combined." (PMID 35963852, 2022). "Over the past decades, significant effort has been devoted to determining the intrinsic mechanism underlying AR action in prostate tumor cells." (PMID 36323713, 2022).
prostate tumors (continued). "In this study, we identified aberrant Wnt/β-catenin signaling activation in hARtg+ prostatic tumor cells, uncovering the regulatory mechanisms underlying AR action in atypical cells to progress to prostatic adenocarcinomas." (PMID 35902588, 2022). "Loss of PPP2R2C expression alone is thought to reprogram prostate tumors towards AR pathway-independent growth and survival." (PMID 33585078, 2021). "Analysis of large tumour cohorts such as The Cancer Genome Atlas (TCGA) revealed that tumours with FOXA1 mutations have a higher AR transcriptional signature compared to normal tissues and other prostate tumour subtypes." (PMID 32946061, 2021). "This study provided new insights into how AR aberrations were also associated with a worse outcome in earlier stages of prostate tumor, even at a lower frequency (up to 20%) than that observed in CRPC." (PMID 33500577, 2021). "In one way, most RB defective prostate tumors are associated with high androgen receptor expression, poor prognosis, and resistance to hormone therapy." (PMID 30885218, 2019). "Androgen receptor expression is prevalent in bone metastases where both full length and shorter AR variants are expressed in metastasized prostate tumor cells." (PMID 31638934, 2019). "This intriguing behaviour of prostate tumor cells was due to marked increase of androgen receptor expression induced by RB loss and consequent expression of AR-target genes." (PMID 31366128, 2019). "PRNCR1 is known to be associated with androgen receptor (AR)-related gene activation in prostate tumor tissues." (PMID 28380453, 2017). "AR-V7 appears to be one of the major AR variants present in human castration-resistant prostate tumors and prostate cancer cell lines." (PMID 29181019, 2017). "A bioanalytical workflow involving streptavidin chromatography and label-free quantitative mass spectrometry was used to identify SBP-AR and associated ligand-sensitive cytosolic proteins/protein complexes linked to AR activation in prostate tumor cells." (PMID 27365400, 2016). "We predict that these mutation-specific human prostate tumor cells will inevitably influence the molecular composition of the AR-interactome." (PMID 27365400, 2016). "The expression of MLPH in primary prostate tumors was significantly lower in those with the G compared with the T allele and correlated significantly with AR protein." (PMID 26411452, 2016). "The combined effects of loss of miRNAs in prostate tumors that regulate AR and Runx in normal prostate tissue, contribute to tumorigenesis in the TRAMP mouse, mirroring that of human disease." (PMID 27634876, 2016). "Overall, our biochemical findings are suggestive of a ligand-dependent association between AR and the Golgi compartment in prostate tumor cells." (PMID 27365400, 2016). "Emerging evidences indicate that prostate tumors can adapt to these androgen-directed therapies, including the new agents, by signaling through constitutively-active AR splice variants (AR-Vs) that lack the functional ligand-binding domain." (PMID 24722067, 2014). "The prostate apoptosis response (Par) factor-related proapoptotic function is associated with prostate tumor progression and sheds light on the effects of the AR pathway on cell survival and apoptosis." (PMID 24565337, 2013). "The variety of mechanisms that can be selected by prostate tumor cells to escape androgen-ablation therapies underlines their plasticity, and suggests that AR expression is mandatory in CRCaP." (PMID 17925854, 2007). "Vaccination of mice with a DNA vaccine encoding the ligand-binding domain of the androgen receptor, a prostate tumor associated antigen, and combined with TLR3 and TLR9 agonists, resulted in secretion of type 1 IFN from antigen-presenting cells and suppression of TRAMP-C1 prostate tumor growth." (PMID 41012179, 2025).